EPCAM (epithelial cell adhesion molecule)
Diseases named in the same sentence as EPCAM in open-access papers (continued):
Sharing a sentence is not in itself a finding about the gene and the disease.
breast carcinoma (continued). "To isolate BCSCs, we used specific antibodies against surface markers (CD44, CD24 or Epithelial Cell Adhesion Molecule (ESA) in a luminal (MCF7) and a triple negative (MDA-MB-231) breast cancer cell line." (PMID 27876836, 2016). "We used primers for the gene sequences of UBB, ESR1 (for luminal or ER/PR+ cancer cells), HER2 and GRB7 (for HER2+ cancer cells), EPCAM, KRT7, KRT8, KRT18, and KRT19, all of which have been commonly discussed for the purpose of breast cancer diagnosis." (PMID 28936247, 2015). "In breast cancer, EpCAM+ CD44+ CD24− lineage− cells are 10 times more likely to form tumors than the EpCAM− CD44+ CD24− lineage− population." (PMID 25636521, 2015). "Thus, EpCAM may be a potential therapeutic target for blocking breast cancer invasion." (PMID 26356670, 2015). "EpCAM expression in early-stage (I, II) and advanced-stage (III) breast cancer tissues was significantly higher than that in normal breast tissues." (PMID 26356670, 2015). "In order to enhance their specific capability to breast cancer cells, ZGG nanoparticles were modified with anti-EpCAM antibody to obtain ZGG-EpCAM nanoprobes." (PMID 30464964, 2015). "EpCAM knockdown led to decreased phosphorylation of Raf and ERK, suppression of malignant behavior of breast cancer cells, and inhibition of the Ras/Raf/ERK signaling pathway." (PMID 26356670, 2015). "On the breast cancer SUM159 cell line, CCAST reveals at least 5 distinct cell states based on two surface markers (CD24 and EPCAM)." (PMID 25078380, 2014). "However, the role of EpCAM in the induction of apoptosis in breast cancer cells remains unclear." (PMID 25019346, 2014). "Many other markers or phenotypes, such as CD133, CD49f, EpCAM, and aldehyde dehydrogenase activity (ALDH), have also been utilized for the isolation of the breast cancer cells with stem cell-like properties." (PMID 25229616, 2014). "EpCAM expression based assay has been FDA approved and widely used to detect circulating tumor cells in breast cancer." (PMID 25265904, 2014). "On the SUM159 breast cancer cell line data, CCAST indicates at least five distinct cell states based on two surface markers (CD24 and EPCAM) and provides a gating sorting strategy that produces more homogeneous subpopulations than previously reported." (PMID 25078380, 2014). "CCAST identifies at least 5 distinct breast cancer cell states in SUM159 and sorted out these pure cell states automatically using only two surface markers, namely EPCAM and CD24." (PMID 25078380, 2014). "This study is consistent with recent reports on xenografts derived from breast cancer and hepatocellular carcinoma (HCC) CTCs, providing the proof of principle about the metastatic potential of EpCAM-positive CTCs." (PMID 25593983, 2014). "In breast cancer, cells with CD44+/CD24−/low/epithelial cell adhesion molecule (EpCAM)+ phenotype were identified as the cancer stem cells." (PMID 25229616, 2014). "CTC were isolated using anti-EpCAM and anti-MUC1 coated magnetic beads from 2 × 5 ml of peripheral blood of 254 early and 51 metastatic breast cancer patients and 30 healthy individuals." (PMID 23497487, 2013). "When incubated in the presence of dextran sulphate and heparin, the anti-EpCAM aptamers DT3 and Ep23 showed highly sensitive staining for T47D, MCF7 and MDA-MB-231 human breast cancer xenografts at a concentration of 100 nM for 15 min at 37°C." (PMID 23460885, 2013). "For example, studies have demonstrated that CTCs may escape EpCAM-based detection due to the epithelial-mesenchymal transition, often a prominent feature of PDACs, and there are many reports for various types of cancers where EpCAM-negative CTCs have been described (e.g. breast cancer;)." (PMID 25346875, 2013). "We found a similar ZEB1-dependent repression of EPCAM expression in human pancreatic and breast cancer cell lines, mediated through direct binding of ZEB1 to the EPCAM promoter." (PMID 23667256, 2013).
breast carcinoma (continued). "In breast cancer, CD44+ CD24−/low ESA+ (epithelial surface antigen, also known as EpCAM) cells were identified as CSCs in a number of solid malignancies." (PMID 24212663, 2011). "In mechanistic studies, we demonstrate that EpCAM expression modulates the JNK signal transduction pathway, and AP-1 transcription factor activity in breast cancer cells." (PMID 22132731, 2011). "Using primary human breast cancer tissues, it has been demonstrated that the CD44+/CD24−/EpCAM+ population of cells can support tumor initiation with as few as 100 cells and have self-renewing, stem-like properties." (PMID 21957456, 2011). "In preliminary studies using a multiplex phosphoprotein assay, specific ablation of EpCAM decreased c-Jun and JNK1 phosphorylation in breast cancer cells." (PMID 22132731, 2011). "Specific ablation of EpCAM results in a significant decrease in JNK phosphorylation in CA1a and MCF-7 breast cancer cells." (PMID 22132731, 2011). "We recombinantly produced all antibodies but murine edrecolomab and investigated them for binding affinity, EpCAM epitope recognition, ADCC and CDC, and inhibition of breast cancer cell proliferation." (PMID 21044305, 2010). "For this purpose we chose two breast cancer cell lines: SKBR3, which has high EpCAM mRNA expression (>7000 AU) and CAL-120, which has low mRNA expression (<500 AU)." (PMID 20838621, 2010). "We determined the distribution of EpCAM mRNA expression across 50 breast cancer cell lines representive of luminal, HER2 amplified and basal-like breast cancers." (PMID 20838621, 2010). "Thus, we tested the surface expression levels of HER2, as well as EpCAM and EGFR, by staining four breast cancer cell lines with these markers individually, as well as in a cocktail." (PMID 41543394, 2026). "Given that this is a lobular breast cancer case, low expression of E-cadherin and EpCAM is not unusual." (PMID 40707771, 2025). "The validated breast cancer surface marker panel consisted of MUC1, EGFR, and EpCAM." (PMID 41404198, 2025). "Among the two tumour models of mouse breast cancer used in this study, TUBO, which exhibited higher and uniform EpCAM expression, responded more favourably to the mEp-NIR-PIT + aPD-1 combination therapy compared to the 4T1 model, which exhibited lower and more heterogeneous expression." (PMID 40792441, 2025). "By employing two distinct aptamers targeting the characteristic proteins of exosomes (CD63, EpCAM), the synergistic effect of the dual aptamers enabled the precise capture of breast cancer exosomes and minimized the interference from nonspecific binding." (PMID 41041069, 2025). "Exosomes from breast cancer cells (MCF-7) and normal mammalian epithelial cells (MCF-10A) were collected and Western blotting was used to detect EpCAM, PSMA, HER2, EGFR, CEA, and CA125, and a marked increase in expression of EGFR, CEA, and CA125 was observed in MCF-7." (PMID 40075875, 2025). "Extension of the study to HCC1500 and MDA-MD-453, two other breast cancer lines with very different characteristics, showed similar differential localization and antagonistic LOF phenotypes, suggesting that these are general properties of the EpCAM/Trop2 pair." (PMID 39572744, 2025). "The plotted deconvolution results obtained from Cell2location showed high agreement with the CTA on the same breast cancer sections, which was further supported by the spatial expression of cell type markers (i.e., PTPRC for immune, FAP for stroma, and EPCAM for tumor) in the same tumor regions." (PMID 40925915, 2025). "EVsderived from breast cancer cells contain elevated levels of proteinssuch as HER2, EGFR, CA 125, CA15–3, PSMA, EpCAM, and MUC1,which are commonly found in breast cancer patients and may serve asEV-derived biomarkers." (PMID 40720603, 2025).
breast carcinoma (continued). "In contrast, EpCAM demonstrated greater efficiency in capturing significant amounts of EVs from the MCF7, BT-474, and SK-BR-3 cell lines, which represent luminal and HER2 breast cancer subtypes with epithelial characteristics." (PMID 39479442, 2024). "In addition, the anti-EpCAM antibody fragment, EpCAM-F800, has shown high specificity and rapid accumulation in CRC and breast cancer." (PMID 39766041, 2024). "Moreover, we investigated the presence of CD45+ CTCs in CRC, breast cancer (BC) and NSCLC patients by detecting the epithelial-mesenchymal markers EpCAM, Vimentin, or abnormal expression of ERBB2, or CK." (PMID 38575583, 2024). "Using DISVT and our machine learning-assisted image analysis platform, we determined the fractions of EpCAM-positive EVs and CD24-positive EVs over captured plasma EVs with CD81 marker in the blood plasma of pilot HER2-positive breast cancer patients and compared to those from healthy donors." (PMID 39513819, 2024). "One major challenge lies in its reliance on EpCAM expression, which limits its ability to detect EpCAM-negative tumor cells, such as breast cancer cells with stem cell-like properties." (PMID 39886667, 2024). "In breast cancer patients, adecatumumab reduced the incidence of metastasis in patients with high EpCAM expression but did not result in partial or complete response in any of the patients." (PMID 38612911, 2024). "The expression of EPCAM increases the expression of stemness markers (NANOG, SOX2, and OCT4) in cancer cells, and EPCAM has been described as a marker of cancer stem cells in colorectal, prostate, pancreatic, and breast cancers." (PMID 36674577, 2023). "Unfortunately, although the authors pointed out that EpCAM is overexpressed in breast cancer CSCs, they did not perform experiments, such as tumorsphere formation assays, to evaluate the inhibitory effects of EpCAM-AsiCs on CSCs." (PMID 36969696, 2023). "Our findings indicate that in 8/10 (80%) of early breast cancer patients that did not relapse no CK-19 transcripts were detected in the EpCAM(+) CTC fraction." (PMID 36690653, 2023). "The three antigens separated breast cancer patients from healthy individuals with an AUC of 0.663 (95% CI: 0.504–0.821) for ROR1, 0.732 (95% CI: 0.586–0.878) for ROR2 and 0.652 (95% CI 0.489–0.814) for EpCAM." (PMID 37430307, 2023). "In a small cohort of prostate and breast cancer patients, we find high inter-patient and temporal intra-patient variability in the expression of tissue specific markers such as ER, HER2, AR, PSA and PSMA and EpCAM." (PMID 37568766, 2023). "CD44+CD24− cell populations have been found to have the greatest tumor-initiating potential in breast cancer and have been used, either alone or in combination with other markers (CD133, EpCAM, CD49f, CD90, and CD61), to identify and isolate breast cancer stem cells (BCSCs)." (PMID 36979915, 2023). "In our present study, we evaluated two panels of transcripts related with the presence of circulating tumor cells (CTCs) (Panel 1: CK19, EpCAM, SCGB2A2 and Panel 2: EMP2, SLC6A8, HJURP, MAL2, PPIC and CCNE2) in two cohorts of breast cancer patients (metastatic and early)." (PMID 36831613, 2023). "Moreover, genetically engineered CAR-T cells have been developed targeting commonly expressed breast cancer antigens such as HER2, EGFR, EpCAM, AXL and c-MET." (PMID 36910138, 2023). "Of note and unlike CD-49f, the expression of the breast cancer stem cell marker CD44 was observed to be increased in the fraction of EpCAM-positive CTCs." (PMID 36823365, 2023). "As expected, isolated cells showed enrichment of CD31 and absence of the breast cancer marker EpCAM by western blot and RT‐qPCR analysis, confirming the purity of HUVEC preparations." (PMID 35656866, 2022).
breast carcinoma (continued). "In this study, we investigated the ability of EpMab-37-mG2a-f to induce ADCC, CDC, and antitumor activities against a breast cancer cell line (BT-474) derived from the luminal B HER2-positive subtype, and a pancreatic cancer cell line (Capan-2), both of which express EpCAM." (PMID 36546899, 2022). "For breast cancer, TGF-β1 was found to promote EMT by upregulating EpCAM via JNK/AP-1 activation." (PMID 36369033, 2022). "In addition, in breast cancer, the additional treatment of a TIM-3 inhibitor together with a bispecific T-cell engager directed against CD3 and EpCAM further enhanced the anti-tumor toxicity of γδ T cells." (PMID 35326415, 2022). "The TT-RBC-NPs enabled enhanced cytotoxic efficacy against EpCAM positive MCF-7 breast cancer over the non-targeted NPs." (PMID 36235009, 2022). "More recently, we have studied the expression of five different BCSC markers (CD44, integrin subunit α6, cadherin-3, EpCAM, and ALDH1) and found significant enrichment for each biomarker in human breast cancer brain metastasis when compared with unmatched primary tumours." (PMID 35326385, 2022). "Thus, thefindings of an extensive study showed that EpCAM expression is detected in 48%of human breast cancer cases.Similarly to HER2, EpCAM is already employed as a target in monoclonalantibody-based immunotherapy (using Removab)." (PMID 35441046, 2022). "In breast cancer, EPCAM expression did not seem to be correlated to EPCAM promoter methylation, while in colon cancer tissue, the unmethylated promoter sequence is correlated to a 1000 fold increase in EPCAM expression in comparison normal tissue." (PMID 36230521, 2022). "This study demonstrated the excellent ability of EINPs to target EpCAM-overexpressed breast-cancer cells in comparison to the non-targeted NPs, resulting in greater cellular binding/uptake." (PMID 35877345, 2022). "The expression of key markers associated with proliferation (MKI67, PCNA, CCNB1, MYBL2, BUB1, CCND1), apoptosis (BCL2, CASP7, CASP8, CASP9, CASP3, BAX, APAF1), differentiation (CDH1, CD24, EPCAM, ESR1, NGFR, RUNX1), and breast cancer stemness (CD44, ITGA6, DNER, ALDH1A3, ABCG2, PROCR) was assessed." (PMID 35183258, 2022). "According to such parameters, six cancer-specific proteins in colon cancer (CEACAM8, CDH17, GLOD5, PPM1E, TRIM16, EPCAM), one in breast cancer (CCR9) and none in prostate cancer were identified." (PMID 36243758, 2022). "The membrane fraction of the ERα+ noninvasive breast cancer cell line ZR‐75‐1 and MCF‐7 was extracted and followed by co‐immunoprecipitation of EpCAM using C‐10, a mouse monoclonal antibody raised against amino acids 24–93 of the EpCAM molecule." (PMID 34240826, 2022). "In the present study, the transcript levels of a 6-gene panel (CCNE2, PPIC, MAL2, EMP2, HJURP, and SCL6A8) previously published as candidate CTC markers, and of epithelial cell lineage-specific (EpCAM, CK19) and breast cancer-specific (SCGB2A2) markers were assessed." (PMID 36074219, 2022). "Analysis by flow cytometry showed binding of the αEpCAM–αCD3 and αEpCAM–αCD28 BiMAb to EpCAM-positive MCF-7 breast cancer cells, whereas irrelevant FAP-specific BiMAb did not bind, as this antigen was not expressed on MCF-7 cells." (PMID 34484225, 2021). "In a breast cancer study, CTC subsets were selected for EpCAM negativity, positivity for stem cell markers (CD44+/CD24−) and combinatorial expression of uPAR/intβ1 because downregulation of these two markers has been directly implicated in breast cancer dormancy." (PMID 34026650, 2021).
breast carcinoma (continued). "The EpCAM antigen used in the maintrac® process is not exclusively expressed on the surface of breast cancer cells, but also on normal epithelial cells, e.g., of the gut and the lung." (PMID 34590615, 2021). "Multiple pre-clinical investigations showed efficacy of NK-CAR cells targeting HER2 in HER2+ breast cancer, tissue-factor in TNBC, epithelial cell adhesion molecule (EpCAM) in both HER2+ and TNBC and epidermal growth factor (EGFR) in all breast cancer subtypes." (PMID 34135901, 2021). "Accordingly, EpCAM+ CTCs counts predict the clinical outcome of patients with metastatic and non-metastatic breast cancer." (PMID 34063272, 2021). "The MCF-7 human breast carcinoma and the C10 feline injection site sarcoma cell lines were used as positive and negative cell controls, respectively, for EpCAM-mediated adhesion." (PMID 33614766, 2021). "We aimed to study the impact of EMT-related markers on a breast cancer cohort and specifically analyze the involvement of Snail, Twist, ZEB1, N-cadherin, Vimentin, GRHL2, E-cadherin, and EpCAM and their respective outcome on both immune infiltration of the TME and clinicopathological features." (PMID 34680248, 2021). "Besides, abnormal glycosylation has been shown to regulate signaling pathways and markers involved in conservation of CSCs, such as EpCAM glycosylation on cell adhesion and EMT in breast cancer, or N-glycosylation on MAPK and PI3/Akt pathway." (PMID 33889547, 2021). "Microfluidic integrated with optical trappings, electrophoresis, dielectrophoretic and immunocapture technology has been reported for the detection of cancer specific exosomes (CD9, CD63, CD53, CD23, EpCAM and, HER2-positive) from blood plasma of breast cancer patients." (PMID 33417986, 2021). "Interestingly, both MCF7 and T47D cells over-expressing ETV7 showed and increased expression of EpCAM, further strengthening our findings on the ETV7-mediated breast cancer stemness." (PMID 34315857, 2021). "Triple negative breast cancer (TNBC) is an aggressive form of breast cancer that expresses a mesenchymal phenotype, but also retains EpCAM expression." (PMID 34209658, 2021). "The subsequent molecular and phenotypic characterization of this subtype in human breast cancers revealed that claudin-low tumors exhibit reduced levels of differentiated luminal cell surface markers (CD24, EpCAM) and have an elevated expression of N-cadherin and vimentin." (PMID 34145248, 2021). "We did not observe any positive IHC staining for EpCAM in the oral tissue from a healthy cat, normal cutaneous epithelium in the section of the mammary tumor, or the tested oral squamous cell carcinoma." (PMID 33614766, 2021). "Two EpCAM-positive cell lines, MCF-7 (a breast cancer cell line) and the CHO–EpCAM cell line used for antibody selections, were used as targets and both Jurkat cells and CD3+ T cells derived from human peripheral blood mononuclear cells (PBMCs) were used as effector cells." (PMID 33127646, 2020). "The choice to use EPCAM derived from a specific characteristic of this marker: it is an epithelial cell adhesion molecule, expressed by solid tumors of epithelial origin, such as non-small-cell lung cancer, breast cancer, or ovarian cancer." (PMID 32391123, 2020). "For example, in breast cancer, CTCs can only be detected in about 60% of the metastatic breast cancer patients, indicating the presence of EpCAM-negative CTCs." (PMID 32046162, 2020). "In addition, CD24, CD44, CD133, EpCAM, and ALDH1 have been documented as beneficial CSC markers in the chemically-induced rat mammary carcinoma model." (PMID 33375383, 2020). "The ability of the DOX-loaded aptamer to transcytose the BBB and selectively deliver the payload to EpCAM-positive tumors was evaluated in an in vitro model and confirmed for the first time in vivo using the MDA-MB-231 breast cancer metastasis model (MDA-MB-231Br)." (PMID 32027209, 2020).